PREX1 (phosphatidylinositol-3,4,5-trisphosphate dependent Rac exchange factor 1)
Diseases named in the same sentence as PREX1 in open-access papers (continued):
Sharing a sentence is not in itself a finding about the gene and the disease.
glioblastoma (continued). "PREX1 therefore has a role in glioblastoma motility in cells from multiple patients, at least within the classical molecular subtype, and this is independent of whether cells have partially or fully compromised PTEN function." (PMID 28051998, 2017). "PREX1 expression is preserved in glioblastoma cells isolated from patients under serum-free conditions and was higher in glioblastoma cells of the classical subtype (PriGO8A, PriGO9A and PriGO7A) than those showing a mesenchymal subtype component (PriGO17A cells)." (PMID 28051998, 2017). "However this inhibition was only partial and it is likely that glioblastoma cells are able to use multiple G protein-coupled receptors to activate PREX1." (PMID 28051998, 2017). "Another Rac GEF that promotes Rac1-mediated invasion in glioblastoma cells is PREX1, which is overexpressed in GBM and responds to the presence of the upregulated Pi3K pathway." (PMID 32089990, 2020). "This analysis also showed that PREX1 is almost never amplified or mutated in glioblastoma." (PMID 28051998, 2017). "We initially focused on PREX1, as it is directly regulated by PIP3 binding and is overexpressed in glioblastoma." (PMID 34624316, 2021). "While PREX1 knockout affected Lgl phosphorylation in one of the two patient-derived glioblastoma cells, motility was impaired in both, suggesting a nonredundant role for PREX1 in glioblastoma cell motility." (PMID 34624316, 2021). "We were able to isolate clones that were confirmed to be PREX1-null by TIDE sequence analysis and Western blotting, showing that PREX1 is not essential for glioblastoma cell growth in cell culture." (PMID 34624316, 2021). "For normal tissue, two samples of normal brain adjacent to glioblastoma tumours and two samples of normal cerebrum were negative for PREX1." (PMID 28051998, 2017). "This study did not assess the function of these Rac GEFs in glioblastoma cells that have invasive properties in vivo and did not assess a potential role for the Rac GEF PREX1 in glioblastoma invasion." (PMID 28051998, 2017). "PREX1 knockout in glioblastoma cells from a second patient did not affect Lgl1 phosphorylation." (PMID 34624316, 2021). "However, knockout of PREX1 in cells from both patients reduced motility, suggesting a nonredundant role for PREX1 in driving glioblastoma invasion." (PMID 34624316, 2021). "PREX1 and ABHD2 have also shown to promote tumor invasion and progression in glioblastoma, while the tumor suppressor BIN1 was found to be regulated by HNRNPA2B1, a putative proto-oncogene in GBM." (PMID 32070274, 2020).
autism (5 papers, 2011 to 2021). Persistent deficits in social interaction and communication and interaction as well as a markedly restricted repertoire of activity and interest as well as repetitive patterns of behavior. "A study on the Chinese Han population revealed that common variations in PREX1 are found in autistic individuals, and PREX1 mRNA levels are lower in the peripheral blood cells of autism subjects." (PMID 32244264, 2020).
lung carcinoma (4 papers, 2018 to 2021). "To date, the roles of ABR, PREX1, DOCK2, and DOCK4 in lung cancer are largely unknown, and the underlying mechanisms remain to be explored." (PMID 34783629, 2021). "The downregulation of ABR, PREX1, DOCK2 and DOCK4 in NSCLC can be induced by promoter methylation, and their methylation profiles might be potential indicators for lung cancer screening." (PMID 34783629, 2021). "Thus, DNA hypermethylation might contribute to the downregulation of ABR, PREX1, DOCK2, and DOCK4 in NSCLC, and the methylation profiles of the four key Rho GEFs may be novel biomarkers for lung cancer screening." (PMID 34783629, 2021).
acute myeloid leukemia (3 papers, 2019 to 2024). Acute myeloid leukemia (AML) is a group of neoplasms arising from precursor cells committed to the myeloid cell-line differentiation. "In a study using a database of human acute myeloid leukemia (AML) cell lines, a genome-wide CRISPR-based screen revealed PREX1 as an AML-specific activator of MAPK signaling in RAS processing." (PMID 30871030, 2019). "Others in which a significant correlation was observed were acute myeloid leukemia in which, as in the case of LGG, elevated PREX1 expression correlated with shorter survival, and kidney renal clear cell carcinoma and lung adenocarcinoma that had the opposite correlation." (PMID 35875157, 2022).
colorectal cancer (3 papers, 2020 to 2025). A primary or metastatic malignant neoplasm that affects the colon or rectum. "Specifically, the phosphorylation state of PREX1 was mapped to Rho GTPase regulation, a pathway experimentally proven to drive cytoskeletal remodeling and metastatic invasion in colorectal cancer." (PMID 40466864, 2025). "In colorectal cancer, the expression level of PREX1 is significantly elevated, and its PTMs are closely related to the migration and invasion capabilities of cancer cells." (PMID 40466864, 2025). "Additionally, high expression of PREX1 is correlated with poor prognosis, indicating its important role in the progression of colorectal cancer." (PMID 40466864, 2025). "Interestingly, seven of the shared significant genes have been associated to colorectal cancers, including UTP23, GREM1, SCG5, SMAD7, CABLES2, LAMA5, and PREX1." (PMID 32245788, 2020).
Obesity (3 papers, 2017 to 2022). Accumulation of substantial excess body fat. "The PREX1 gene maps to a locus that is linked to type 2 diabetes, and single-nucleotide variations in the perigenic region of PREX1 are associated with the likelihood of obesity developing into diabetes." (PMID 36342857, 2022). "The human PREX1 gene maps to a gene locus on chromosome 20q13.1 that has been linked to type 2 diabetes in many studies, and SNPs in the perigenic region of PREX1 have been proposed to associate with the likelihood of obesity developing into type 2 diabetes." (PMID 33923452, 2021).
astrocytoma (2 papers, 2021 to 2022). "The 26 essential signaling genes, identified in the P-Rex1-dependent astrocytoma cell context, were further examined in terms of their co-expression with PREX1 in LGG patients." (PMID 35875157, 2022).
bipolar disorder (2 papers, 2011 to 2018). A disorder of the brain that causes unusual shifts in mood, energy, activity levels and the ability to carry out day-to-day tasks. "The PREX1 and ZNF536 genes have been shown to be associated with MDD and bipolar disorder, respectively." (PMID 30034349, 2018).
gastric cancer (2 papers, 2018 to 2023). A primary or metastatic malignant neoplasm involving the stomach. "In this study, the impact of silencing Rac1 and Prex1 on transforming growth factor-beta 1-induced epithelial–mesenchymal transition and apoptosis of human gastric cancer cells MGC-803 and MKN45 was investigated." (PMID 37434402, 2023). "One of the limitations of this study is that it mainly explored the effect of silencing Rac1 and Prex1 on EMT in human gastric cancer in vitro." (PMID 37434402, 2023). "Silencing Rac1 and Prex1 could inhibit epithelial–mesenchymal transition, reduce cell viability and migration, and promote apoptosis in human gastric cancer cells." (PMID 37434402, 2023). "At present, the roles and mechanisms of Rac1 and Prex1 in gastric cancer cell EMT are still unknown." (PMID 37434402, 2023). "The RNA interference vectors of Rac1 and Prex1 genes were constructed to investigate the impact of silencing Rac1 and Prex1 expression on EMT, apoptosis, and cell viability of TGF-β1-treated gastric cancer cells." (PMID 37434402, 2023).
glioma (2 papers, 2013 to 2022). A benign or malignant brain and spinal cord tumor that arises from glial cells (astrocytes, oligodendrocytes, ependymal cells). "Analysis of the predictive value of the PREX1 signaling hub signature in two independent LGG datasets from the Chinese Glioma Genome Atlas (CGGA) demonstrated a significant high risk score that correlated with shorter survival." (PMID 35875157, 2022). "Lower Grade Glioma was the type of cancer in which half of the patients with higher PREX1 expression exhibited the highest statistical correlation with shorter survival." (PMID 35875157, 2022). "In experimental murine gliomas caused by autocrine PDGF signaling, PREX1 was found upregulated as a putative promoter of cell transformation." (PMID 35875157, 2022). "The first suggestion of an association arose in a genetic screen to identify key factors in glioma progression in vivo, which highlighted PREX1 as a gene which cooperates with PDGF signalling to promote metastasis." (PMID 23382862, 2013).
liver cancer (2 papers, 2024). An epithelial or non-epithelial malignant neoplasm that arises from the liver. "Moreover, biological functional assays were performed to further investigate the roles of PREX1 in liver cancer cell lines." (PMID 38903921, 2024). "Furthermore, our findings revealed that PREX1 may shape the immune microenvironment of liver cancer and enhance sensitivity to immunosuppressive treatment." (PMID 38903921, 2024).
pulmonary fibrosis (2 papers, 2016 to 2021). Chronic progressive interstitial lung disorder characterized by the replacement of the lung tissue by connective tissue, leading to progressive dyspnea, respiratory failure, or right heart failure. "In a bleomycin-induced mice pulmonary fibrosis model, Prex1 transcript level was significantly elevated after bleomycin administration in comparison with saline (GSE40151)." (PMID 34349645, 2021). "Four independent pulmonary fibrosis microarray datasets from public gene expression datasets of the Gene Expression Omnibus database (GEO) were analyzed for PREX1 mRNA levels compared to non-diseased controls." (PMID 34349645, 2021). "Moreover, increased PREX1 mRNA levels were found in lung myofibroblasts from patients with idiopatic pulmonary fibrosis compared to donors using noncontractile matrices (GSE11196)." (PMID 34349645, 2021).
adenoma (1 paper, 2016). A neoplasm arising from the epithelium. "We identified hypermethylated CpG sites in the following genes: L3MBTL1, NKX6-2, PREX1, TRAF7, PRDM14, and NEFM with the number of CpG sites being 14, 17, 10, 16, 6, and 6, respectively, after pairwise analysis of normal versus adenoma, adenoma versus cancer, and normal versus cancer." (PMID 27688749, 2016).
Arthritis (1 paper, 2023). Inflammation of a joint. "Thus, this study suggested that circ-PREX1-miR-140-3p-WNT5B axis might be a novel molecular regulation mechanism of paeoniflorin exerting anti-arthritis role in KOA chondrocytes." (PMID 37817257, 2023).
ischemic heart disease (1 paper, 2023). "Prex1 and Irx3 are suggested as potential modifier genes of cardiac Cu content, while Ctsa, Mmp2, and Armcx1 may closely be related to ischemic heart disease." (PMID 36818345, 2023).
Kashin-Beck disease (1 paper, 2023). Disabling osteochondrodysplasia with osteosclerosis, cone-shaped metaphysis, and shortening of the diaphysis. "CircRNA hsa_circ_0060652, derived from PREX1 gene (referred as circ-PREX1) is highly expressed in knee joint chondrocytes of OA than that from Kashin-Beck disease." (PMID 37817257, 2023). "Besides, circ-PREX1, one of the top 10 most upregulated circRNAs, was upregulated to 5.73-fold in human KOA chondrocytes versus patients with Kashin-Beck disease." (PMID 37817257, 2023).
leukemia (1 paper, 2024). A malignant (clonal) hematologic disorder, involving hematopoietic stem cells and characterized by the presence of primitive or atypical myeloid or lymphoid cells in the bone marrow and the blood. "Finally, we detected the expression of marker genes of macrophage and NK cells, and found that five genes of FCAR, FCGR3A, PREX1, S100A8 and S100A9 all were significantly overexpressed in the leukemia cells of HAP1 compared with that in the normal stroma cells of HS-5 (p < 0.05)." (PMID 39583114, 2024).
metastatic cancer (1 paper, 2022). A carcinoma which has spread from the original site of growth to another anatomic site. "Of the GPCRs and their agonists that showed clear contrast in their Spearman correlation values comparing the high and low PREX1 expression groups, we found a known chemokine-GPCR pair, CXCL9-CXCR3, already described as relevant in metastatic cancer progression." (PMID 35875157, 2022).
metastatic disease (1 paper, 2024). "PREX1 is highly expressed in oral SCC (OSCC), and is associated with metastatic disease and poor prognosis." (PMID 38191532, 2024).
myeloid malignancies (1 paper, 2018). "Intronic-PREX1 (20q13.13), a reported locus predisposing to MM was confirmed to have contribution to excess MGUS risk in interaction with SETBP1, a well-established candidate predisposing to myeloid malignancies." (PMID 30134812, 2018).
osteosarcoma (1 paper, 2021). A usually aggressive malignant bone-forming mesenchymal neoplasm, predominantly affecting adolescents and young adults. "Distinct from the identification of ABR, PREX1 and DOCK2 in non-cancer cells, DOCK4 identification was initially reported in osteosarcoma cells, in which DOCK4 was deleted during tumor progression." (PMID 34783629, 2021).
psychosis (1 paper, 2024). "Moreover, the first gene in the list, namely PREX1 has been reported to be linked with brain-related conditions, such as aberrant neuronal polarity and psychosis-related behaviors, in case of over-expression." (PMID 39580456, 2024).
tubulovillous adenoma (1 paper, 2016). An epithelial neoplasm morphologically characterized by the presence of a villous and a tubular architectural pattern. "For the PREX1 gene (NM_020820), we identified 27 methylated CpG sites in the promoter region in tumor samples and 6 methylated CpG sites in tubulovillous adenoma samples." (PMID 27688749, 2016).
uterine carcinosarcoma (1 paper, 2022). A usually aggressive malignant neoplasm arising from the uterine corpus and less often the cervix. "We also found that the PREX1 signaling hub signature indicated higher risk score for shorter survival in uveal melanoma and uterine carcinosarcoma (TCGA studies), which were not initially addressed as they were not included in the OncoLnc platform that we used for the initial screening." (PMID 35875157, 2022).
vascular malformation (1 paper, 2021). A non-neoplastic disorder that is the result of defects of vascular morphogenesis. "Assuming a spontaneous de novo mutation event, one of the identified variants found in the PREX1, UBE3B, PCDHGA2, and ZSWIM6 genes may represent a possible candidate pathogenic variant for this rare form of vascular malformation." (PMID 33652974, 2021).
cancer (43 papers, 2013 to 2026). A tumor composed of atypical neoplastic, often pleomorphic cells that invade other tissues. "Elevated PREX1 expression has been linked to migratory and invasive phenotypes of cancer cells, and conversely, PREX1 knockdown suppresses cell migration and invasion." (PMID 38191532, 2024). "PREX1 encodes a multidomain activator of the Rac GTPase known to promote cell migration and metastatic dissemination of cancer cells." (PMID 35875157, 2022). "Phosphatidylinositol-3,4,5-trisphosphate-dependent Rac exchange factor 1 (P-Rex1) has been implicated in cancer growth, metastasis, and response to phosphatidylinositol 3-kinase (PI3K) inhibitor therapy." (PMID 28698809, 2017). "PREX1, which is one of the few genes altered by all the three ClC-5 mutations studied, has been identified as an important factor in tumor cell invasion and metastasis in a number of cancer models." (PMID 33987651, 2021). "Furthermore, several GEFs including PREX1 and Vav2 as well as Vav3 are reported to be over-expressed and associated with carcinoma progression." (PMID 29454349, 2018). "Phosphatidylinositol-3,4,5-trisphosphate-dependent Rac exchange factor-1 (P-Rex1), as one of the members of Rac-GEFs, has been proven to play a critical role in cancer progression and metastasis through a feedback loop of Rac1 activation." (PMID 36892683, 2024). "Phosphatidylinositol-3,4,5-trisphosphate-dependent Rac exchange factor-1 (P-Rex1), as one of the members of Rac-GEFs, has been proven to play a critical role in cancer progression and metastasis." (PMID 36892683, 2024). "Our results demonstrated that mRNA expression of PREX1 was significantly higher in several malignant tumors than in normal tissues, including LIHC." (PMID 38903921, 2024). "Among the upregulated GEFs, PREX1 was chosen for subsequent analysis due to of its known pro-invasive role in cancer." (PMID 38191532, 2024). "ΔNp63α indirectly controls PREX1 promoter transcriptional activity and downregulates its expression, which in turn inhibits activation of Rac1 and reduces cancer cell invasion." (PMID 38191532, 2024). "Studies have suggested that PREX1 plays a role in mediating oncogenic pathway activation and controlling various biological mechanisms in different types of cancer, including liver hepatocellular carcinoma (LIHC)." (PMID 38903921, 2024). "By the way, paeoniflorin functioned in diverse cancers and inflammatory disorders, it would be great helpful to determine the reciprocal interaction between paeoniflorin and circ-PREX1 in these diseases." (PMID 37817257, 2023). "PREX1 mRNA expression values, obtained from the cBioPortal for Cancer Genomics, were higher in LGG and LAML patients compared to KIRC and LUAD." (PMID 35875157, 2022). "Given the metastatic role of P-Rex1 demonstrated in preclinical cancer models, we analyzed 21 TCGA transcriptomic datasets to identify those cancer types in which patient survival correlated with PREX1 expression." (PMID 35875157, 2022). "Given this role in promoting cell motility, PREX1 has been studied for a potential role in cancer cell invasion." (PMID 28051998, 2017). "Previous studies revealed that PREX1 is prominently upregulated in multiple human cancers." (PMID 38191532, 2024). "Amplification or epigenetic dysregulation of PREX1 may contribute to its overexpression in some human cancers." (PMID 38191532, 2024). "Endogenous PREX1 knockdown reduces Rac1 activity and cancer cell invasion in SCC cells." (PMID 38191532, 2024). "Since various genes of the signature positively correlated with PREX1 in more than 20 types of cancer, we addressed whether, as an integrated signature, it revealed increased risk in these independent datasets." (PMID 35875157, 2022).